OR2G6 (olfactory receptor family 2 subfamily G member 6)
Description:
Odorant receptor.
Tractability: Antibody: UniProt places it where antibodies can reach, with medium confidence; UniProt predicts a signal peptide or a membrane-spanning region; its Gene Ontology location is reachable by antibodies, with medium confidence.
Gene: Protein-coding gene on chromosome 1 (248,508,073 to 248,527,337, forward strand). Ensembl gene ENSG00000188558.
Subcellular location: Cell membrane
Pathways (Reactome):
Sensory Perception: Expression and translocation of olfactory receptors
Gene Ontology:
Molecular function: protein binding; olfactory receptor activity; G protein-coupled receptor activity
Biological process: detection of chemical stimulus involved in sensory perception of smell; G protein-coupled receptor signaling pathway
Cellular component: plasma membrane; membrane
Genetic constraint (gnomAD): Loss-of-function variants: 0 observed, 0.68 expected, observed/expected ratio (o/e) 0, 90% interval 0 to 1.8. That is too few expected variants to judge how well the gene tolerates losing a copy. Missense variants: 456 observed, 411.04 expected, observed/expected ratio (o/e) 1.11, 90% interval 1.03 to 1.2. Synonymous variants: 181 observed, 162.65 expected, observed/expected ratio (o/e) 1.11, 90% interval 0.99 to 1.26.
Homologues: Orthologues: chimpanzee OR2G6 (90% identical), guinea pig OR2G6 (84% identical). Paralogues in human: OR2G2 (64% identical), OR2G3 (63% identical), OR2Y1 (58% identical), OR2C3 (58% identical), OR2B2 (57% identical), OR2C1 (56% identical), OR2H2 (55% identical), OR2B11 (54% identical), OR2W3 (54% identical), OR2W1 (54% identical), OR2B3 (54% identical), OR2J1 (54% identical), and 80 more.